DKK2 (dickkopf Wnt signaling pathway inhibitor 2)
Diseases named in the same sentence as DKK2 in open-access papers (continued):
Sharing a sentence is not in itself a finding about the gene and the disease.
tumor (continued). "Although these results demonstrate that DKK1 and DKK2 regulate growth of some tumor cell types, the effects of DKK1 and DKK2 on tumor angiogenesis has not been thoroughly studied." (PMID 24091497, 2014). "Conversely, tumor vessel perfusion was increased in DKK2 Tg mouse tumors, to levels 123 % of wild-type littermates." (PMID 24091497, 2014). "Conversely, DKK2 Tg mice tumor vessels had more pericyte coverage (134 % of wild-type levels) and SMCs (167 % of wild-type levels)." (PMID 24091497, 2014). "Nevertheless, the detailed mechanisms of DKK2-regulated perivascular cell coverage of tumor neovessel remain to be elucidated." (PMID 24091497, 2014). "We studied DKK1 and DKK2 effects on tumor vessel functionality by injecting lectin into DKK Tg mice bearing B16F10 tumors and quantifying vessel staining, a surrogate of vascular perfusion, in subsequently harvested tumors." (PMID 24091497, 2014). "In conclusion, our data indicate that DKK1 and DKK2 regulate both tumor angiogenesis and perivascular coverage." (PMID 24091497, 2014). "Using an adenoviral infection and EC-specific transgenic mice, we show that DKK1 and DKK2 differentially regulate structure and functionality of tumor blood vessels, in addition to tumor angiogenesis." (PMID 24091497, 2014). "DKK2 increases tumor growth and metastasis through transcriptional upregulation of matrix metalloprotease-1 in Ewing’s Sarcoma." (PMID 24091497, 2014). "Together, these data demonstrate that DKK1 negatively, and DKK2 positively, regulates tumor angiogenesis." (PMID 24091497, 2014). "Conversely, Ad-DKK2 transfection accelerated tumor growth [5,194 ± 422 vs. 3,170 ± 397 mm3 (p < 0.001)] and shortened survival time in these mice (p < 0.001)." (PMID 24091497, 2014). "In conclusion, DKK1 and DKK2 regulate tumor vessel functionality, resulting in changes of tumor hypoxia status." (PMID 24091497, 2014). "In the present study, we investigated the effects of DKK1 and DKK2 on tumor growth and angiogenesis." (PMID 24091497, 2014). "To elucidate the mechanism underlying the tumor-derived DKK2-mediated impairment of CD8+ T cell cytotoxicity, we investigated whether DKK2, a canonical Wnt signaling inhibitor, induced CD8+ T cell dysfunction by suppressing this pathway." (PMID 41542770, 2026). "Since DKK2 is secreted, we quantified its levels in tumor cell conditioned media (CM)." (PMID 41542770, 2026). "Furthermore, in vivo data showed that anti-Dkk2 antibody (5F8) not only inhibited tumor proliferation and growth, but also notably reversed the acceleration of Nat10-OE tumor growth." (PMID 41542770, 2026). "Furthermore, we discovered that Fusobacterium mortiferum and 5-AVA can activate the Wnt/β-catenin signaling pathway by inhibiting DKK2, thereby promoting tumor growth." (PMID 40340623, 2025). "Given that DKK2 expression is intestinal tumor specific, inhibition of DKK2 may have promising therapeutic outcomes in the treatment of metastatic colon cancer." (PMID 38659853, 2024). "However, in this context, Dkk2 was utilized as an immune evasion tool secreted by tumors to suppress cytotoxic immune cell activation and tumor destruction via an atypical, Wnt signaling independent pathway." (PMID 36599670, 2023). "In addition, DKK2 mRNA and LINC00326 levels were significantly associated with the 96 tumor samples (r = 0.8754, P < 0.0001)." (PMID 36747258, 2023). "Given that anti-VEGF signaling is an approved therapy for human CRC, we tested if the combination therapy including VEGFR blockade and DKK2 blockade in the MC38 tumor syngeneic graft model could have a synergetic effect." (PMID 32559853, 2020). "Besides the regulation of DKK2 on cytotoxic immune cells, we also observed that 5F8 antibody treatment impaired tumor vasculature at the late stages of tumor progression." (PMID 32559853, 2020). "Thus, we also investigated the combination effect of DKK2 blockage on VEGF-A/VEGFR blockade-mediated suppression of tumor progression." (PMID 32559853, 2020).
tumor (continued). "Taking these results together, DKK2 can promote angiogenesis, and anti-DKK2 antibody treatment may inhibit tumor angiogenesis directly and indirectly at the late stage of tumor progression." (PMID 32559853, 2020). "In conclusion, these data suggest that DKK2 presents prognostic value and might have effects on tumor progression." (PMID 31583260, 2019). "Tumor cells with control shRNA or Dkk2 shRNA were implanted into flank of C57/BL mice." (PMID 31372243, 2019). "We found that anti-DKK2 antibody suppressed the tumor growth." (PMID 31372243, 2019). "In addition, an elevated expression of DKK2 predicts poorer prognosis of patients and positively correlated with poor tumor differentiation." (PMID 31583260, 2019). "To study the effect of DKK2 on tumor progression in vivo, we performed tumor orthotopic experiment." (PMID 31372243, 2019). "Here we studied whether the tumor suppressive function of DKK2 was related to its effects on this pathway." (PMID 28467796, 2017). "Thus, our findings demonstrate that DKK2 functions as a tumor suppressor through inhibiting cell proliferation and inducing apoptosis via regulating Wnt signaling during breast tumorigenesis." (PMID 28467796, 2017). "Cells expressing DKK2 recovered cell adherence and contacts with each other, however, the control cells exhibited a scattering pattern, indicating that DKK2 might be involved in tumor cell EMT." (PMID 28467796, 2017). "Finally, our genetic and functional data confirms that DKK2 functions as a tumor suppressor in the liver." (PMID 27203079, 2016). "Similarly, the expression of DKK2, a key player of ES invasiveness and osteolytic tumor growth, was greatly reduced by JQ1." (PMID 26623725, 2016). "Besides the higher incidence of tumors Dkk2−/− mice exhibited a highly significantly increased volume of the tumor nodules in comparison to WT mice." (PMID 25826080, 2016). "DKK2 was previously identified to be a critical mediator of osteolytic tumor growth in ES." (PMID 27363011, 2016). "Interestingly, DKK2 increased tumor angiogenesis, which was correlated with accelerated B16F10 tumor growth." (PMID 24091497, 2014). "We hypothesized that DKK1 and DKK2 effects on tumor growth may be due to altered tumor angiogenesis." (PMID 24091497, 2014). "In addition, DNMT3B was confirmed to be directly regulated by miR-766-3p several years ago, and DNA methylation of some tumor suppressors such as DKK2 could be decreased by transfecting miR-766-3p-expressing viruses." (PMID 34093648, 2021). "Although it was previously shown to be possible as independent event, hypomethylation of DKK2 in higher grades of tumor versus semimethylation pattern in low grades may be indicating that overexpression of DKK2 gene is necessary for tumor transition from low to high grades." (PMID 33346226, 2020). "Interestingly, we found a synergetic effect on suppressing tumor progression, as well as extending survival, by a combination administration of DKK2 blockade with a suboptimal dose of anti-VEGFR via activation of CD8+ T/NK cells and impaired tumor angiogenesis." (PMID 32559853, 2020). "As DKK2 is an important component in the Wnt pathway and gene set enrichment analysis (GSEA) also indicated that epithelial mesenchymal transition significantly enriched in the DKK-highly expressed group, we first investigated whether DKK2 have an impact on the tumor cell's migration." (PMID 31583260, 2019). "Our results suggest that DKK2 may be a tool secreted by tumor cells to modulate immune status." (PMID 31583260, 2019). "No methylation was observed in SK-BR-3 and T47D cells with DKK2 downregulation, which might be caused by the heterogeneity of tumor cells, and suggests that other mechanisms such as histone deacetylation might be also involved." (PMID 28467796, 2017).
tumor (continued). "In addition, using an EFT cell line SK-ES1 cells, we also demonstrated that the expression of DKK1 and DKK2 is mutually exclusive, and the ectopic expression of DKK1, but not DKK2, resulted in the suppression of tumor growth in immuno-deficient mice." (PMID 19247449, 2009). "Neutralizing DKK2 with the 5F8 enhances the efficacy of anti–PD-1 therapy by reactivating CD8+ T cells and inhibiting tumor growth." (PMID 41542770, 2026). "scRNA-seq data further revealed diminished cholesterol accumulation in tumor-infiltrating CD8+ T cells from Nat10cKO mice versus Nat10fl/fl controls, implicating Dkk2 in modulating CD8+ T cell cholesterol homeostasis." (PMID 41542770, 2026). "In order to analyze transcriptome changes by Dkk2 knockout in each cell type of metastasized tumors, we performed single-cell RNA sequencing (scRNA-seq) analysis on liver metastasized AKP and KO tumor cells." (PMID 38659853, 2024). "In order to analyze transcriptome changes by Dkk2 knockout in each cell type of metastasized tumors, we performed scRNA-seq analysis on liver metastasized AKP and KO tumor cells." (PMID 39535280, 2024). "We recently showed that DKK2, a canonical Wnt signaling pathway antagonist, which is upregulated in CRC, promoted tumor progression by suppressing the activation of immune effector cells." (PMID 32559853, 2020). "In the other hand, defining the exact role of Wnt pathway as proliferative or antiproliferative signaling modules can clarify the possible character of DKK2 and DKK4 genes as weather they are tumor suppressor genes or oncogenes in pathogenesis of OSCC." (PMID 33346226, 2020). "DKK2, which is upregulated in CRC, was recently found to suppress host immune responses, and its blockage effectively impeded tumor progression in benign genetic CRC models in our previous study." (PMID 32559853, 2020). "More work is needed to further elucidate the mechanism by which DKK2 regulates endothelial cells and its crosstalk with VEGF-A/VEGFR pathway during tumor progression." (PMID 32559853, 2020). "In contrast of DKK2 gene, there was significant correlation between DKK4 promoter methylation and tumor grade (P=0.03)." (PMID 33346226, 2020). "Target genes AXIN2, DKK2 and FGF9, well known for their potential to promote tumor formation and progression in vitro as well as in vivo in CRC, were significantly downregulated in response to SARB46,47." (PMID 31097715, 2019). "The loss of APC in intestinal tumor cells upregulated the expression of DKK2 through β-catenin pathway, which, together with its receptor LRP5, provided an unconventional mechanism for tumor immune evasion." (PMID 31372243, 2019). "We previously demonstrated DKK2 to be an agonist of the canonical WNT/β-catenin pathway and critical mediator of osteolytic tumor growth in ES." (PMID 27363011, 2016). "To address possible mechanisms of LOH for the DKK2 gene, we analyzed the cytogenetic changes in eight HCC cases that were heterozygous for DKK2 haplotype 1 in their tumor adjacent tissue." (PMID 27203079, 2016). "Using allelic retention status in the HCC tumor as a criterion, three genes (UNC5C, DKK2, and ZGRF1) from the LOH region were evaluated for further investigation." (PMID 27203079, 2016). "Taken together, our data indicate that DKK1 and DKK2 effects on tumor growth involve DKK-modulated angiogenesis and altered tumor neovascular structure." (PMID 24091497, 2014). "We analyzed tumor vessel density of Ad-DKK1- and Ad-DKK2-transfected tumors, in comparison with Ad-Mock transfectants." (PMID 24091497, 2014). "To confirm the effect of DKK1 and DKK2 on tumor angiogenesis, we used DKK1 Tg and DKK2 Tg mice that we generated for our previous study." (PMID 24091497, 2014). "Our finding that ectopic expression of PRDM5 leads to the inhibition of WNT/β-catenin signaling in tumor cells, probably through upregulating DKK1, DKK2, and WNT5A, suggests a novel mechanistic link between PRDM5 and WNT signaling in human tumorigenesis." (PMID 22087297, 2011).
tumor (continued). "In the metastasis-associated neoplastic cell states, we detected robust expression of neural crest (ZIC1, OLIG3), mesenchymal (MSX2, GDF6), and metastasis-related (DKK2) genes in addition to adrenergic genes (e.g., PHOX2B) that were shared with primary tumor cell states." (PMID 41279557, 2025). "This indicated downregulation of DKK2 mRNA in the tumor tissues, which was confirmed by western blotting, together with a negative correlation between DKK2 downregulation and miR-657 levels (r = − 0.5362, P < 0.0001)." (PMID 36747258, 2023). "Interestingly, the tumor suppressor MEG3 promotes tumor progression through targeting miR-4261, modulating the expression of DKK2, β-catenin, Bcl-2, and c-Myc, thus activating the Wnt/β-catenin signaling pathway." (PMID 35448163, 2022). "The sub‐clustering of ECs revealed six subtypes, including extra‐alveolar capillary EC (cEC) (FCN3+EDN1+PLVAP+), alveolar cEC (HPGD+EDNRB+IL1RL1+), arterial EC(GJA5+FBLN5+DKK2), lymphatic EC (CCL21+TFF3+FABP4), INSR+ tumour EC (INSRhiHSPG2+PLVAP+), and ACKR1+ tumour EC (ACKR1+SELP+IL1R1+)." (PMID 35184398, 2022). "Interestingly, its relationship with tumor immunity evasion in some subsets of melanoma and colorectal tumors, where DKK-2 depletion activates natural killer (NK) cells and CD8+ T lymphocytes and impedes tumor progression, has also been described." (PMID 34451907, 2021). "Consistent with our previous study, DKK2 blockade increased the number of apoptotic cells without significant effects on tumor cell proliferation." (PMID 32559853, 2020). "Flow cytometry analysis of tumor infiltrated leukocytes revealed that the DKK2 blockade did not significantly affect the infiltration of CD45+, CD4+ T cells, CD8+ T or natural killing (NK) cells in the tumors." (PMID 32559853, 2020). "We also found that the combination of anti-DKK2 can be used with anti-VEGFR in a mouse CRC model and notably DKK2-blockade can augment anti-tumor efficacy of sub-optimal dosage of anti-VEGFR by further reducing tumor angiogenesis and enhancing anti-tumor immunity." (PMID 32559853, 2020). "Based on this, we performed a combined administration of DKK2 blockade with sub-optimal anti-VEGFR treatment and observed a synergetic effect on suppressing tumor angiogenesis and progression, as well as extending survival, better than those of every single therapy." (PMID 32559853, 2020). "Hypomethylation of DKK2 and DKK4 genes in higher grades of OSCC samples may indicate the pivotal role of their expression in tumor cells invasion and progression through modulation of Wnt signaling pathway." (PMID 33346226, 2020). "Hypomethylation of DKK2 and DKK4 genes in higher grades of OSCC tissue samples may indicating their overexpression and thereby tumor progression through suppressing Wnt pathway." (PMID 33346226, 2020). "Sequencing of the DKK2 gene in the tumor tissue of these cases indicated that only haplotype 1 was retained in the tumor tissue, regardless of the copy number of 4q21 signals." (PMID 27203079, 2016). "Opposite to DKK1, DKK2 enhances pericyte and SMC coverage of B16F10 tumor vessels." (PMID 24091497, 2014). "Tumor angiogenesis, as measured by microvascular density, was decreased in DKK1 Tg mice to levels 68 % of those seen in control animals, whereas vessel density in DKK2 Tg mice was increased to levels 127 % of those seen in wild-type animals." (PMID 24091497, 2014). "Interestingly, DKK2, a homolog of DKK1, increased tumor neovessel formation and perfusion, consequently accelerating tumor growth." (PMID 24091497, 2014). "Vessel-specific LRP6 expression in tumors supports the idea that DKK1 and DKK2 expression does not affect tumor cell proliferation." (PMID 24091497, 2014). "Unlike DKK1, beta-catenin staining in tumor blood vessels of DKK2 Tg mice was significantly increased compared to wild-type." (PMID 24091497, 2014). "Similar pattern of tumor growth was observed in endothelial-specific DKK1 and DKK2 transgenic mice." (PMID 24091497, 2014).
tumor (continued). "That DKK2, but not DKK1, activates tumor angiogenesis is supported by the observation that DKK2 enhances retinal angiogenesis and induces neovessel formation in several ex vivo assays." (PMID 24091497, 2014). "Because improved vascular functionality is the aim of tumor vessel normalization approaches, DKK1 and DKK2 effects on angiogenesis and vessel functionality that regulates tumor hypoxia might be purposefully exploited in developing novel cancer treatments." (PMID 24091497, 2014). "Interestingly, tumor vascular density and perfusion were significantly decreased by DKK1 but increased by DKK2." (PMID 24091497, 2014). "The up-regulation of DKK2 consequently leads to a suppression of DKK1 and thus possibly contributes to EFT phenotype indirectly by interfering with the suppressive function of DKK1 on tumor growth." (PMID 19247449, 2009). "Similarly, the tumor suppressor lncRNA GAS5 was shown to target Wnt/β-catenin signaling and attenuate ABCB-1-mediated adriamycin resistance via miR-221-3p/Dickkopf-related protein 2 (DKK2) pathway regulation." (PMID 32967267, 2020). "But we are not sure whether DKK2 directly bind the receptors on immune cells and function or act through other cell types such as tumor cells and pancreatic stellate cells (PSCs)." (PMID 31583260, 2019). "Furthermore, GSEA predicts negative correlation between tumor immunity invasion and DKK2 expression." (PMID 31583260, 2019). "Consistent with the accelerated tumor growth a significantly increased proliferation rate could be detected in untreated, non-tumorous Dkk2−/− deleted livers." (PMID 25826080, 2016). "These oncogenic functions were shown to be regulated by miR-21-mediated downregulation of several established tumor suppressor molecules, including PTEN, programmed cell death 4 (PDCD4), tropomyosin, reversion-inducing cysteine-rich protein with kazal motifs (RECK), and dickkopf 2 (DKK2)." (PMID 26504785, 2015). "Our results suggested that DKK2 could not functionally substitute for DKK1 tumor-suppressive effect in EFT." (PMID 19247449, 2009). "Because knockdown Dkk2 did not affect the growth of LCC cells in in vitro culture, the impaired tumor progression in the shDKK2 group might alter tumor microenvironment." (PMID 31372243, 2019). "In contrast to DKK2, stable knock down of HOXD genes did not significantly influence bone invasiveness, although suppression of HOXD10, HOXD11 and HOXD13 seemed to slightly reduce the invasive growth potential of tumor cells in the bone marrow." (PMID 27363011, 2016). "As we demonstrated in this study, ectopic expression of DKK1 in EFT cells resulted in the inhibition of tumor growth in SCID mice, whereas DKK2 expression did not and even possibly accelerated tumor growth in vivo, demonstrating that DKK2 does not act as a counterpart of DKK1." (PMID 19247449, 2009).